NPC1 (NPC intracellular cholesterol transporter 1)
Diseases named in the same sentence as NPC1 in open-access papers (continued):
Sharing a sentence is not in itself a finding about the gene and the disease.
Ebola (6 papers, 2015 to 2024). "Zoonosis of a virus is often followed by finer tuning of replication, as observed in the 2014 Ebola outbreak, in which the variant A82V enabled more efficient receptor NPC1 usage." (PMID 34228725, 2021). "The current data provide further insight into the complex transport functions of NPC1, a lysosomal membrane protein required for cellular cholesterol homeostasis as well as for susceptibility to Ebola and other filoviruses." (PMID 26646182, 2015). "This approach may also provide insights into the recent outbreak and spread of Ebola, because the virus uses the NPC1 protein to infect host cells (and deficiency in NPC1 protects against infection)." (PMID 26110763, 2015). "Indeed, Ebola sensitivity was restored when NPC1-deficient Chinese Hamster Ovary (CHO) cells were transfected with a plasmid encoding only the luminal loop 2 portion of NPC1." (PMID 26646182, 2015). "NPC1 is also the primary host factor responsible for Ebola, and other filovirus, entry into host cells." (PMID 38696518, 2024). "In the case of Ebola, NPC1 is hijacked by the virus to cross the endolysosomal membrane for cell entry." (PMID 38388172, 2024). "Previous results had demonstrated that NPC1 mediates the entry of Ebola, and some small molecular inhibitors block the infection of Ebola by disturbing the interactions between NPC1 domain C and Ebola primed GP9." (PMID 28117364, 2017). "Recently, a study demonstrated that U18666a interacts with the NPC1 sterol-sensing domain (SSD) to inhibit NPC1 function and cholesterol transport; however, the authors emphasized that the inhibition of Ebola requires 100-fold higher concentrations of U18666A." (PMID 28117364, 2017).
retinal degeneration (6 papers, 2014 to 2023). Degeneration of the retina. "NPC1 deficient mouse showed signs of retinal degeneration including lipofuscin accumulation in the pigment epithelium and impaired electroretinography." (PMID 36262888, 2022). "Homologs of two genes causing cholesterol storage disorders, Npc1a / NPC1 and Lip4 / LIPA, were independently confirmed as loss-of-function enhancers of αSyn-induced retinal degeneration." (PMID 37200393, 2023). "Sensory malfunctions in NPC1 such as retina degeneration and hearing loss have already been reported in an NPC1 mouse model." (PMID 30154701, 2018). "In Npc1 mutant mice, retinal degeneration including impaired visual function, lipofuscin accumulation in the pigment epithelium and ganglion cells as well as photoreceptor defects has been found." (PMID 25472750, 2014). "In this study, we examined NPC1-P, clinically healthy NPC1-MC, and HC using OCT to (i) identify retinal degeneration in NPC disease using a non-invasive OCT technique and (ii) to investigate for possible subclinical retinal atrophy in NPC1-mutation carriers (MC)." (PMID 32222928, 2020). "In this study, we examined NPC1-P, clinically asymptomatic NPC1-MC, and HC using OCT to identify retinal degeneration and to evaluate the potential eligibility of OCT measures as biomarkers of neurodegeneration and disease progress." (PMID 32222928, 2020). "We observed a non-significant trend of retinal degeneration in NPC1-MC correlating with subclinical motor abnormalities." (PMID 32222928, 2020). "Second, for asymptomatic heterozygous NPC1-MC, there was no significant retinal degeneration." (PMID 32222928, 2020).
Sandhoff disease (6 papers, 2016 to 2021). A lysosomal disorder from the GM2 gangliosidosis family, caused by biallelic pathogenic variants in the HEXB gene, characterized by GM2 ganglioside accumulation in the nervous system and progressive central nervous system degeneration. "Here we investigated the effect of mutations in the Npc1 and Hexb genes on the circadian axis in mouse models of NPC1 and Sandhoff disease." (PMID 26467605, 2016). "In this study, we have investigated the effects of AL in mouse models of NPC1 and Sandhoff disease and in patients to better understand its therapeutic potential and to gain insights into its MOA." (PMID 33738443, 2021). "In order to investigate whether the specific pathologies related to the LSDs NPC and Sandhoff disease influence circadian behaviour, we examined mouse models of both these disorders, the Npc1 null mutant (Npc1nih) and Hexb knockout (Hexb−/−)." (PMID 26467605, 2016). "A range of defective autophagic lysosomal pathways occur in LSDs; from the abnormal enzymatic processing in Sandhoff disease to the non-enzymatic deficiencies as seen in NPC1." (PMID 26467605, 2016). "A similar upregulation of genes in IFN pathway has been observed in microglia from neuronopathic Gaucher and Krabbe disease mice, but not in NPC1 or Sandhoff disease animals." (PMID 31883529, 2019).
amyotrophic lateral sclerosis (5 papers, 2019 to 2023). Amyotrophic lateral sclerosis (ALS) is a neurodegenerative disease characterized by progressive muscular paralysis reflecting degeneration of motor neurons in the primary motor cortex, corticospinal tracts, brainstem and spinal cord. "The RNA expression profile in MLIV microglia showed a mixed neuroprotective/neurotoxic pattern, similar to what was previously observed in NPC1 microglia, amyotrophic lateral sclerosis (ALS), and glioblastoma." (PMID 31883529, 2019).
breast carcinoma (5 papers, 2022 to 2025). "In breast cancer, the loss of miR-200c promotes increased NPC1 expression, and NPC1 correlates with ER− and higher-grade disease." (PMID 35884604, 2022). "Recently, emerging evidence has revealed elevated NPC1 expression across various malignancies such as breast cancer, gastric cancer, liver cancer etc." (PMID 40510474, 2025). "NPC1 increase facilitates extracellular cholesterol uptake and is necessary for the invasion of ErbB2 expressing breast cancer spheroids and ovarian cancer organoids, indicating a regulatory role for NPC1 in the process." (PMID 37420029, 2023). "Based on the expression of NPC1 in breast cancer and its known roles in cholesterol metabolism and mTOR signaling pathways, we sought to determine if NPC1 supports tumor-promoting characteristics in vitro." (PMID 35884604, 2022). "It is possible that cholesterol auxotrophic breast cancers have elevated NPC1 protein as a mechanism to support exogenous cholesterol availability." (PMID 35884604, 2022). "Supporting the relevance of NPC1 in breast cancer, a query of NPC1 in publicly available patient datasets demonstrated higher NPC1 mRNA in patients with basal, ER−, and high-grade tumors relative to ER+ low-grade disease." (PMID 35884604, 2022). "By western blot, TNBC cell lines had higher expression of NPC1 relative to ER+ breast cancer cell lines, and immunohistochemistry demonstrated NPC1 expression in both primary tumor and lung metastasis in an MMTV-driven mouse model of breast cancer." (PMID 35884604, 2022). "Interestingly, activated ErbB2-induced macropinocytosis-mediated cholesterol uptake in breast cancer cells is connected to upregulation of NPC1 and can thus be blocked by inhibiting it." (PMID 39243069, 2024). "Overactivation of ErbB2 signaling leads to activation of the transcription factor MZF1 which in turn increases the expression of the lysosomal cholesterol transporter NPC1 and activates macropinocytosis, increasing the macropinocytotic uptake of extracellular cholesterol in breast cancer cells." (PMID 39243069, 2024). "Our results showed that expression of constitutively active and standard treatment resistant p95ErbB2 in breast cancer cells induces macropinocytosis and increases the expression of cholesterol trafficking protein NPC1 and results in increased extracellular cholesterol uptake." (PMID 37420029, 2023). "This work suggests NPC1 as a potential target and a mediator of breast cancer aggression." (PMID 35884604, 2022). "Our novel finding that NPC1 silencing can suppress P70-S6K signaling in some breast cancer cell lines suggests that mTOR may link lysosomal cholesterol with mitochondria in these cells." (PMID 35884604, 2022). "We found that NPC1, which encodes the lysosomal cholesterol transporter Niemann–Pick type C1 is highly expressed in TNBC as compared to estrogen receptor-positive (ER+) breast cancer, and is significantly elevated in high-grade disease." (PMID 35884604, 2022). "We demonstrated that NPC1 is directly targeted by microRNA-200c (miR-200c), a potent suppressor of EMT, providing a mechanism for its differential expression in breast cancer subtypes." (PMID 35884604, 2022). "To validate the results, we used the CRISPR/sgRNA system to deplete NPC1 in different human cancer cell lines and observed a decreased cell growth in MM ARP-1 and RPMI-8226 (another MM cell line), HepG2, SKOV3, colon cancer HCT116, and breast cancer MDA-MB-231 cells." (PMID 41013744, 2025). "However, expression of NPC1 in breast cancer datasets does not strongly correlate with genes in these pathways or the pathways themselves, suggesting that NPC1 is not upregulated due to broadly increased cholesterol or lysosomal signaling." (PMID 35884604, 2022).
epilepsy (5 papers, 2015 to 2025). A brain disorder characterized by episodes of abnormally increased neuronal discharge resulting in transient episodes of sensory or motor neurological dysfunction, or psychic dysfunction. "This possibility is consistent with the finding that Npc1 loss of function leads to mTORC1 over‐activation, which in turn stimulates the microglia proliferative activity, as recently demonstrated in a mouse model of epilepsy." (PMID 36322609, 2022). "However, the unexpected effect of CDX on the GABAergic synaptic transmission is of special interest as a disturbance plays, for example, a crucial role in epilepsy and, moreover, as CDX is currently under investigation as a treatment for NPC1 in humans." (PMID 26392920, 2015).
Gaucher disease (5 papers, 2017 to 2024). Gaucher disease (GD) is a lysosomal storage disorder encompassing three main forms (types 1, 2 and 3), a fetal form and a variant with cardiac involvement (Gaucher disease - ophthalmoplegia - cardiovascular calcification or Gaucher-like disease). "In 2 cases where the biochemical diagnosis of Gaucher disease was made due to the low levels of beta-glucosidase enzyme in leukocytes, the smMIP based assay detected pathogenic variant in the NPC1 and NPC2 gene in either case." (PMID 38730490, 2024). "In two cases, biochemical diagnosis suggested Gaucher's disease, however, the smMIP based assay identified a causative variant in the NPC1 gene." (PMID 38730490, 2024). "Earlier work also described accumulation of GPNMB positive foamy cells in the liver of Npc1−/− mice, resembling Gaucher cells during a primary GCase deficiency (Gaucher disease)." (PMID 33802460, 2021). "Accumulation of p62/SQSTM1 has been reported in the endosomal/lysosomal fraction of npc1-/- mouse brain lysates, cultured fibroblasts of Fabry patients, mucolipidosis type II, III and type IV (MLIV) fibroblasts, muscle fibers of Pompe disease, and brain of Gaucher disease mice model." (PMID 36928510, 2023).
GM2 gangliosidosis (5 papers, 2017 to 2025). A group of recessively inherited diseases characterized by the intralysosomal accumulation of G(M2) GANGLIOSIDE in the neuronal cells. "NPC1 has a unique combination of iron-related characteristics because it shares commonalities with both iron deficiency anemia and inflammatory induced anemia and other LSDs such as GM2 gangliosidosis." (PMID 37065726, 2022). "In comparison with GM1/GM2 gangliosidosis mice,Npc1-/- mice exhibited more severe hematological abnormalities, increased circulating hepcidin, abnormal hepatic pro-inflammatory cytokines profiles, erythropoiesis and erythrophagocytosis defects." (PMID 37065726, 2022).
Insulin resistance (5 papers, 2011 to 2021). Increased resistance towards insulin, that is, diminished effectiveness of insulin in reducing blood glucose levels. "mRNA levels of Npc1 in blood cells have been previously proposed as a potential early biomarker of increased risk of developing insulin resistance." (PMID 34579137, 2021). "NPC1 haploinsufficiency also promotes weight gain and metabolic features associated with insulin resistance." (PMID 29273013, 2017). "Results from this second study were similar to the initial study using the BALB/cJ NPC1 mouse model, since an Npc1 gene-diet interaction was found to promote both weight gain and metabolic features associated with insulin resistance." (PMID 22043166, 2011). "Considering these data, we speculate that the metabolic complications associated with reduced NPC1 expression may be due, in part, to decreased GLUT4 expression in adipose since adipose-specific KO of GLUT4 confers insulin resistance and glucose intolerance." (PMID 24752197, 2014). "Indeed, GWAS data and genetic studies in mice have uncovered a link between insulin resistance and NPC1." (PMID 24752197, 2014).
Lipid storage disease (5 papers, 2017 to 2023). "The lipid storage disease Niemann Pick type C (NPC) causes neurodegeneration owing primarily to loss of NPC1." (PMID 37815467, 2023). "What is more, NPC1 is a lipid storage disease that affects virtually all cells and provides a much more dramatic outcome than that seen in discrete HD alterations." (PMID 35886975, 2022). "From lipid-storage diseases, such as NPC1, we can learn more about the cellular and molecular mechanisms underlying neurodegeneration." (PMID 31500175, 2019).
Lysosomal disease (5 papers, 2009 to 2023). "In NPC1 and other lysosomal diseases, the persistent accumulation of cholesterol in late endosomes/lysosomes leads to aberrant lysosomal clustering in the cell center." (PMID 29146937, 2017). "Interestingly, JIP4 silencing reduced clustering in NPC1 cells, suggesting that this pathway may be involved in the accumulation of the cholesterol-laden lysosomes observed in lysosomal diseases." (PMID 29146937, 2017). "Neuro-inflammation is also an important component of many lysosomal diseases, and upon IHC staining of CD68, a CNS inflammatory marker, we noted reduced labeling in brains of end-stage CD-treated Npc1−/− mice compared to end-stage untreated Npc1−/− mice (data not shown)." (PMID 19750228, 2009). "Our finding that CD is beneficial in reducing cholesterol and GSLs in neurons lacking either NPC1 or NPC2 proteins, but not in neurons in GM1 gangliosidosis or MPS IIIA, may be revealing of the importance of cholesterol's mobility in the NPC-affected cell compared with other lysosomal diseases." (PMID 19750228, 2009).
mucolipidosis type IV (5 papers, 2016 to 2025). A lysosomal disease characterized by psychomotor delay, progressive visual impairment, and achlorhydria. "Furthermore, the expression level of Ccl5 (RANTES) was increased in Hexa-/-Neu3-/- mice, similar to mouse models of the Niemann Pick type C (Npc1-/-), Gaucher (Gba-/-) and mucolipidosis type IV (Mcoln1-/-), and this increase was reduced after KD and PG treatments." (PMID 40019557, 2025). "Similarly, defects in lysosomal membrane proteins such as NPC1, LAMP2 and MCOLN1 cause Niemann-Pick type C (NPC), Danon and Mucolipidosis type IV (MLIV) diseases, respectively." (PMID 32375321, 2020).
neuroblastoma (5 papers, 2013 to 2020). Neuroblastoma (NB) is the most common solid, extracranial childhood tumor. "Here, we show that CtsB/L inhibition in CHO and in human neuroblastoma SH-SY5Y cells as well as CtsB and CtsL genetic depletion also affects NPC1 and/or NPC2 and causes their sequestration and accumulation of intracellular free cholesterol." (PMID 27902765, 2016). "These include SH-SY5Y neuroblastoma cells and human embryonic stem cells, which resemble the phenotype only in some aspects of the NPC1 disease." (PMID 24044630, 2013). "The observed changes were also analyzed in human neuroblastoma SH-SY5Y cells which showed increased filipin staining upon PADK-treatment and statistically significant increase of LC3II and NPC1 levels." (PMID 27902765, 2016). "The accumulation pattern of cholesterol in the herein described cells was comparable to accumulations described in a NPC1 knock-down mouse model, and SH-SY5Y neuroblastoma cells." (PMID 24044630, 2013).
sphingolipidosis (5 papers, 2017 to 2025). An inherited metabolic disorder that affects the lysosomal degradation of the spinhgolipids. "For the purpose of this review, NPC1 will be considered as a sphingolipidosis, because in addition to cholesterol it accumulates sphingolipids, and since it shares symptoms and pathogenic mechanisms with the sphingolipidoses Niemann-Pick types A and B." (PMID 32260582, 2020). "Recent studies have demonstrated a synaptic failure also in sphingolipidosis, while in NPC1 there are significant defects in synaptic transmission both at glutamatergic and GABAergic synapses, due to an impairment of synaptic vesicle trafficking." (PMID 28513549, 2017).
cholestasis (4 papers, 2021 to 2025). Impairment of the bile flow caused by obstruction within the liver, or outside the liver in the bile duct system. "We describe nine cases of infantile-onset NPC with various genetic mutations in the NPC1 gene, which presented with neonatal cholestasis." (PMID 35455589, 2022). "NPC1 protein was increased in the livers of patients with cholestasis, as well as in mice with toxic liver injury." (PMID 40722778, 2025).
Krabbe disease (4 papers, 2019 to 2025). A lysosomal disorder that affects the white matter of the central and peripheral nervous systems. "Given the well-documented pathogenic role played by excessive inflammasome activation in a variety of neurodegenerative conditions, we conclude that our findings strongly suggest inflammasome activation as a likely pathogenic factor common to all the LSDs studied here: Krabbe disease, SD and NPC1." (PMID 36519759, 2023).
liver cancer (4 papers, 2025). An epithelial or non-epithelial malignant neoplasm that arises from the liver. "To determine whether the association of NPC1 overexpression with poor prognosis was unique to MM, we analyzed the GEO Chen’s liver cancer dataset." (PMID 41013744, 2025). "Our results highlighted the prognostic relevance of NPC1 expression in liver cancer and suggested a possible function in various cancer types." (PMID 40881173, 2025). "Univariate Cox regression and log-rank tests were used to examine the prognostic role of NPC1 in liver cancer." (PMID 40881173, 2025). "Overexpression of NPC1 in human highly metastatic liver cancer cells (MHCC)-97H and Huh7 cells increased proliferation and cell viability." (PMID 40722778, 2025). "Cholesterol metabolism differs in males and females, and was also shown to contribute to sex-specific disparities in liver cancer; however, whether this translates to NPC1 expression is unknown." (PMID 40722778, 2025). "We used the Kaplan-Meier Plotter to reveal a strong positive correlation between high NPC1 expression and poor OS, RFS, and DFS in liver cancer." (PMID 40881173, 2025).
liver failure (4 papers, 2019 to 2021). A liver disease characterized by the liver losing or has lost all of its function. "Broad clinical manifestations of NPC1 include liver failure, pulmonary disorder, neurological deficits, and psychiatric symptoms." (PMID 33256498, 2021). "Further evaluation of altered miR-155 expression would be needed to determine whether the decreased expression in the spleen is related to the activation of immune cells and increased expression in the liver related to liver failure in NPC1." (PMID 30870990, 2019).